FOXC2 (forkhead box C2)
Diseases named in the same sentence as FOXC2 in open-access papers (continued):
Sharing a sentence is not in itself a finding about the gene and the disease.
tumor (continued). "At pHi 7.7, several of the unique enriched peaks and genes with higher expression dependent on pH-sensing by FOXC2-His122 are known tumor promoting genes." (PMID 40464693, 2025). "FOXC2 expression correlated significantly with lymph node involvement (p = 0.048) and tumor type (p = 0.042), indicating its potential role as a marker of advanced disease and specific histological subtypes." (PMID 40781106, 2025). "FOXC2 can inhibit the expression of E-cadherin, and N-cadherin has been proved to promote tumor in OSCC." (PMID 37237299, 2023). "Together, these cell line, patient and PDTX data indicate that VM is enriched in the aggressive subtypes of human tumors and that combined tumor-endothelial and core FOXC2-target gene expression can identify VM proficient tumors." (PMID 37499655, 2023). "Control shRNA tumors showed only ~10% reduction in tumor volume in response to B20 whereas suppression of Foxc2 drastically flattened tumor growth curves upon B20 treatment, reducing tumor volume ~70% relative to vehicle." (PMID 37499655, 2023). "Foxc2 mRNA levels were also elevated in 4T1 cells derived from lung metastases when compared to primary tumor-derived cells, consistent with prior studies implicating Foxc2 in metastatic dissemination." (PMID 37499655, 2023). "Building on the work of others, our single cell RNA-Seq (scRNA-Seq) analyses indicate that exposure to hypoxia in vivo promotes expression of the Foxc2 transcriptional program and acquisition of endothelial-like state in tumor cells." (PMID 37499655, 2023). "Taken together these data indicate that FOXC2 and its accompanying transcriptional program are upregulated in VM-proficient tumor cells." (PMID 37499655, 2023). "Gene expression analysis of established cell lines, patient-derived tumor xenografts (PDTXs), and patient tumors suggest that FOXC2-driven VM is prevalent in aggressive sub-types of many solid tumors regardless of tissue of origin." (PMID 37499655, 2023). "This process is regulated by transcription factors in tumor cells (Snail 1, Slug, ZEB1, Twist, FOXC2, etc.)and signaling pathways from the tumor microenvironment (WNT, Notch, Hedgehog, TGFβ, FGF, EGF, HGF signaling, etc.)." (PMID 38139030, 2023). "After m5C modulation and binding to m5C readers, such as YBX1, the transcriptional activity of PIK3R1, PCYT1A and FOXC2 mRNA was increased, while tumor-suppressive p57Kip2 mRNA was destabilized as a result of m5C modulation in the 3’-UTR." (PMID 37325635, 2023). "Here, we exploit these, and their VM-incompetent siblings, to identify the transcription factor FOXC2 as a key driver of vasculogenic mimicry that promotes ectopic expression of endothelial genes in tumor cells." (PMID 37499655, 2023). "Survival analysis of tumor bearing mice confirmed that animals with Foxc2 knockdown 4T1-TVM tumors significantly benefited from B20 treatment compared to control 4T1-TVM animals." (PMID 37499655, 2023). "Here we show that the transcription factor, Foxc2, promotes VM in diverse solid tumor-types by driving ectopic expression of endothelial genes in tumor cells, a process which is stimulated by hypoxia." (PMID 37499655, 2023). "FOXC2 appears to achieve this through the transcriptional regulation of endothelial gene expression in tumor cells, leading to their acquisition of endothelial-like properties." (PMID 37499655, 2023). "FOXC2 is a novel independent biological marker for predicting tumor progression and survival because of its prognostic significancy and association with clinicopathological features." (PMID 36425886, 2022). "FOXC2 acts as a key mediator of tumor initiation and progression, involving tumor proliferation, migration, invasion, metastasis, and EMT." (PMID 36425886, 2022).
tumor (continued). "Analogous to its role in embryonal angiogenesis and lymphangiogenesis, FOXC2 plays a critical role in promoting the growth of new vessels thereby establishing the obligatory blood supply for tumor progression." (PMID 36230774, 2022). "We found that downregulation of FOXC2 decreased the tumor volume, tumor weight, and Ki-67 positivity of SGC7901/ADR cells receiving ADR treatment." (PMID 33869020, 2021). "Our findings link the stemness, conferred through EMT, to the acquisition of endothelial cell traits and the augmentation of tumor angiogenesis in a FOXC2-dependent manner." (PMID 33889304, 2021). "FOXC2 knockdown abrogated the potentiating effects of HMLE-Snail cells on MCF-7 tumor growth and vascularization, and compromised endothelial transdifferentiation of mesenchymal cells cultured in endothelial growth medium." (PMID 33889304, 2021). "Gozo MC reported that FOXC2 was frequently overexpressed and augmented tumour propagation and metastasis in OS." (PMID 32249539, 2020). "Recently we have shown that active PI3K signaling decreased p11 expression in several tumor cells via the FOXC2 transcription factor." (PMID 33297495, 2020). "Ultimately, we knocked down endogenous Ang-2, using its shRNA, to elucidate the role of FOXC2 in tumor development." (PMID 32508532, 2020). "In tumor cells, FOXC2 overexpression has been shown to promote proliferation, epithelial-mesenchymal transition (EMT), metastases and drug resistance." (PMID 32698337, 2020). "Together, our results suggest that ZNF750 plays a tumor suppressive role via DANCR/miR-4707-3p/FOXC2 axis that works in a ceRNA manner in ESCC." (PMID 32341351, 2020). "FOXC2 levels were also increased in metastatic PCa tumors compared to primary tumor tissue in three clinical datasets." (PMID 31379747, 2019). "Tumour‐induced osteogenesis promotes growth of the metastatic tumour cells in the bone 35 and FOXC2 is found to induce osteogenesis." (PMID 31464093, 2019). "The PROX1 expression was found in 25.8% (42/163) of patients with OSCC by immunohistochemistry and was markedly associated with the local progression of the tumor (T classification), clinical stage, LVD, nodal metastasis, and expression levels of FOXC2." (PMID 30115834, 2018). "Among the 62 tumor samples, the proportion of FOXC2-positive cells was significantly (p = 0.0005) for T3-T4 tumors (94.9%; 37 of 39) than for T1-T2 samples (56.5%; 13 of 23)." (PMID 30279969, 2018). "Taken together, a large body of evidence now suggests that the modes of action of FOXC1 and FOXC2 share some phenotypic features through various signaling pathways that promote tumor progression and metastasis." (PMID 30360388, 2018). "The frequency of FOXC2 expression differed significantly (p = 0.011) across the four tumor stages; 0% (0/7) of T1 samples, 39% (9/23) of T2 samples, 50 % (37/73) of T3 samples, and 59% (49/82) of T4 samples were positive for FOXC2 expression." (PMID 30279969, 2018). "The frequency of FOXC2 expression was 31.1% (14/45) in T1-T2 tumor samples and 50% (8/16) in T3-T4 tumor samples." (PMID 30279969, 2018). "Reportedly, FOXC2 is a tumor-progressive factor in various malignancies and is closely associated with metastasis and prognosis." (PMID 30115834, 2018). "FOXC2 was previously reported to function as an EMT-related gene during not only tumor progression but also organ repair." (PMID 29801468, 2018). "Previous studies have revealed that epithelial-to-mesenchymal transition (EMT) is involved in tumor invasion and metastasis, and the forkhead box protein C2 (FOXC2) has been shown to promote tumor cell proliferation, invasion, and EMT." (PMID 29801468, 2018). "FOXC2 was expressed in 46.0% of all samples, in 32.4% of early-stage tumor samples, and in 55.6% of late-stage tumor samples." (PMID 30279969, 2018). "In Pten-null mice, Notch signaling was not required for the initiation of PCa, but did promote EMT and FOXC2 (forkhead box protein C2)-dependent tumor metastases." (PMID 29152153, 2017).
tumor (continued). "Many of the EMT inducing transcription factors such as Snail1, Snail2/slug, ZEB1, ZEB2, FOXC2 and TWIST1 have been associated with tumor invasion and metastasis." (PMID 29202800, 2017). "A functional study demonstrated that FOXC2 promoted cell growth, cell migration, and tumor formation in nude mice, whereas knockdown of FOXC2 significantly reversed these effects." (PMID 29258163, 2017). "FOXC2, which is the first gene expressed from the podocyte-committed region, was highly expressed in the epithelial-predominant tumours containing abundant renal vesicle (RV)-like structures." (PMID 29040332, 2017). "Observations in LNCaP and DU145 cells show that ZEB1 mediates the effect of FOXC2 on tumor-initiating potential and drug resistance, traits that are often correlated with EMT." (PMID 29623961, 2017). "The expression of mesenchyme forkhead 1 (FOXC2) in the primary tumor correlates with the degree of lymph node metastasis." (PMID 29254233, 2017). "Overexpression of FOXC2 correlates with tumor invasion and metastasis and is reported to promote EMT of tumor cells." (PMID 27999212, 2017). "Inhibition of either PKCα or FOXC2 is sufficient to rescue p120-catenin expression and trigger relocalization of p120-catenin and E-cadherin to the cell membrane, resulting in reduced tumor cell migration and invasion." (PMID 29216867, 2017). "To quantitatively analyze the role of FOXC2 in tumor propagation, we injected limiting dilutions of SJSA1-EV and SJSA1-FOXC2 cells subcutaneously into nude mice and allowed for tumor development up to 16 days." (PMID 27634875, 2016). "Downregulation of FOXC2 decreases anchorage-independent growth and invasion in vitro and lung metastasis in vivo, while overexpression of FOXC2 increases tumor propagation in vivo." (PMID 27634875, 2016). "At the same time, the expression of FOXC2 gene was found to be decreased in tumor tissue compared to the healthy tissues (p = 0.0181)." (PMID 25575813, 2015). "FOXC2 is pivotal for the migration and tubular transformation of vascular endothelial cells and for tumor angiogenesis, functions that are elicited by the activation of VEGF-A signaling." (PMID 24647631, 2014). "By immunohistochemistical analysis, Prox1 was shown to be closely associated with tumor progression (T factor and clinical stage), nodal metastasis, and LVD, and FOXC2 expression was shown to be significantly correlated with MVD in OSCCs." (PMID 24647631, 2014). "The PDGFR-β inhibitor sunitinib reduced tumor growth and metastasis of FOXC2-expressing tumor cells." (PMID 23986719, 2013). "A few pathways and molecules have been so far implicated in the regulation of epithelial plasticity in basal-like tumours, including the Wnt signaling, Forkhead 1 factor FOXC2, and lysyl oxidase-like 2 (LOXL2)." (PMID 23555842, 2013). "FOXF1 and FOXC2 are part of the forkhead gene family, which are transcription factors originally identified as potential tumor suppressor genes." (PMID 23074687, 2012). "Tumor growth and angiogenesis were remarkably lower in the FoxC2+/– mutants, which confirms that FoxC2 has an essential role in tumor angiogenesis." (PMID 22174714, 2012). "VEGF-A expression was also impaired in B16 tumors from FoxC2+/– mice, and this decline likely limits tumor neovascularization." (PMID 22174714, 2012). "The tumoral endothelium in human and mouse express FOXC2, and Foxc2 +/− heterozygous mutant mice display reduced tumor growth due to a decrease in neoangiogenic activity." (PMID 22481918, 2012). "The overexpression of the closely related FOXC2 gene has been found to promote tumour metastasis and invasiveness." (PMID 20338046, 2010). "Interestingly, FOXC2 promotes tumour aggressiveness and poor prognosis in basal-like triple-negative breast cancers via activation of EMT, stemness and drug resistance." (PMID 40764669, 2025).
tumor (continued). "Furthermore, the transcription factor FOXC2 promotes VM by driving the expression of endothelial genes in tumor cells, a process amplified by hypoxia within the tumor microenvironment." (PMID 40136656, 2025). "For example, PGE2 binding with EP1 activates protein kinase C (PKC)/nuclear factor-κB (NF-κB)/human forkhead box protein C2 (FOXC2) and EGFR/PI3K signaling pathways, which increases intercellular adhesion molecule-1 (ICAM-1), thereby causing tumor growth and migration." (PMID 38704736, 2024). "Similarly, while control tumors showed ~5% reduction in tumor volume with Axitinib treatment, Foxc2 knockdown tumors showed ~80% reduction in size with treatment." (PMID 37499655, 2023). "This suggests that FOXC2 confers a quasi-endothelial identity upon tumor cells that may be acquired via an intermediate mesenchymal state." (PMID 37499655, 2023). "Furthermore, the expression of EMT genes and oncogenes, including Mmp3, Mmp7, Mmp8, Fn1, Vim, Foxc2, Ctnnb1, Lgr5, Axin2, cMyc, Ccnd1, and Yap1, was significantly high in the tumor of cohoused Nlrp12–/– compared with WT mice." (PMID 37581937, 2023). "FoxC2 is a TF involved in mesenchyme development and tumor progression." (PMID 36406265, 2022). "FOXC2 is known to aid in tumor progression by promoting epithelial-mesenchymal transition (EMT), stem cell differentiation, proliferation and migration, drug resistance, and resistance to anoikis, a form of programmed cell death that occurs when cells detach from the extracellular matrix." (PMID 36230774, 2022). "As we observed upregulation of FOXC2 expression in hypoxic tumor cores, we first examined the expression of FOXC2 and HIF-1α in immortalized (HMLE) and RAS-transformed (HMLER) human mammary epithelial cells, following exposure to DFX, an iron chelator known to function as a hypoxia-mimetic." (PMID 33889304, 2021). "Taken together with the known functions of FOXC2 in the regulation of physiological and tumor angiogenesis, we hypothesized that FOXC2 may play a central role in the capacity of cells that have undergone EMT to acquire an endothelial phenotype." (PMID 33889304, 2021). "Moreover, FOXC2 is an important factor involved in tumour cell proliferation, differentiation, and invasion." (PMID 34484336, 2021). "In order to ascertain whether FOXC2 is necessary for the ability of cells that have undergone EMT to augment tumor growth and angiogenesis in vivo, we co-mixed HMLE-Snail-shControl or HMLE-Snail-shFOXC2 cells with RFP/luciferase-labeled MCF-7 cells." (PMID 33889304, 2021). "In addition, subcutaneous injection of B16 melanoma cells into Foxc2 haploinsufficient mice has been shown to lead to the impaired formation of tumor blood vessels and, accordingly, compromise tumor growth." (PMID 33889304, 2021). "In addition, we report herein that FOXC2 expression is induced in the hypoxic tumor cores, commensurate with the induction of EMT." (PMID 33889304, 2021). "Regarding the female dogs, we sequenced 79 BC-related genes, and those with high number of variants shared by tumor fragments and plasma were GATA3 and mTOR (missense), SFRP1 (frameshift insertion), BRCA2 (multi hit), FOXC2, ATM, TGFBR3, and BRIP1 (missense and multi hit mutations)." (PMID 34680380, 2021). "We next evaluated the effect of FOXC2 on tumor growth by in vivo optical imaging in NOD/SCID mice." (PMID 32508532, 2020). "Furthermore, the tumor size and weight in the FOXC2 OE Ang-2 KD group were significantly reduced (P < 0.01), indicating that FOXC2 accelerates growth and metastasis of HCC through regulation of Ang-2." (PMID 32508532, 2020). "The high expression of FOXC2 in HCC is correlated with tumor malignancy and poor prognosis, suggesting that FOXC2 may be an important prognostic factor for HCC." (PMID 29801468, 2018).
tumor (continued). "Samples (n = 163) were evaluated from the tumors of patients with oral squamous carcinoma; 31.0% (9/29) of stage T1 tumor samples, 22.4% (17/76) of stage T2 tumor samples, 22.9% (8/35) of stage T3 tumor samples, and 17.4% (4/23) of stage T4 tumor samples were positive for FOXC2 expression." (PMID 30279969, 2018). "Data for each of the four tumor stages were assessed independently; 37.5% (3/8) of stage T1 samples, 20% (5/25) of stage T2 samples, 31.7% (13/41) of stage T3 samples, and 50% (5/10) of stage T4 samples were positive for FOXC2 expression." (PMID 30279969, 2018). "Secondly, because tumor size is an important determinant of the likelihood of synchronous metastasis also in patients with ≤7-cm ccRCCs, the relationship between the tumor size and the expression of FOXC2 and CLIP4 should be clarified." (PMID 27283491, 2016). "Microscopic tumor nodules were observed in several lung sections of mice injected with 143B sh1 cells but the nodules were FOXC2 positive, indicating that they arose from cells with incomplete knockdown of FOXC2." (PMID 27634875, 2016). "Next, we examined by qRT-PCR if FOXC2 knockdown in U2OS cells affects the expression of several genes known to be enriched in tumor-propagating cells, such as the cell surface marker CD133, multidrug resistance pump ABCG2, Notch signaling receptor ligands JAG1 and BMP4, and chemokine receptor CXCR4." (PMID 27634875, 2016). "Among the upregulated genes, we identified several oncogenes (Ets2, Fyn, Fos, Rab30 and Src), various tumor markers (Cyp1b1, Gpa33, Cd47, Fam129a, st7l, chka, Lgalsbp, Antxr1 and Ly6a) and other genes related to tumor promotion (Cxcl10, Trim25, Grn, Foxc2, Bmp7 and Irs1)." (PMID 23936067, 2013). "Considering that FOXC2 also plays a critical role during embryonic blood and lymphatic vessel development, there is also evidence for the involvement of this transcription factor during tumor growth and angiogenesis." (PMID 22481918, 2012). "FoxM1 is expressed in glioma and pancreatic cancer cells and promotes angiogenesis by regulating VEGF expression, FoxO1/3/4 act as tumor suppressors in prostate cancer and leukemia, and recent evidence suggests that FoxC2 is a key factor in tumor development and disease progression." (PMID 22174714, 2012). "The declines in tumor growth and vascularity observed in FoxC2+/– mice were also associated with abnormally low levels of PDGF-B, which is likely attributable to the impaired growth of smooth muscle cells surrounding the tumor blood vessels." (PMID 22174714, 2012). "We revealed that expression levels of PART1 and FOXC2 are significantly upregulated and the miR-3529-3p expression level significantly decreases in the serum while high expression level of PART1 is positively associated with tumour size, BCLC stage, and TNM stage." (PMID 34484336, 2021). "Indeed, a significant proportion of cells, within the 5–7 mm tumor cores, displayed nuclear localization of FOXC2, consistent with its activation as a transcription factor and the engagement of the EMT program in response to hypoxic conditions in the outgrowing tumors." (PMID 33889304, 2021). "Furthermore, the PDGFR-β inhibitor sunitinib reduced tumor growth and metastasis of FOXC2-expressing tumor cells, but given our findings it is most likely the effects mediated by sunitinib in these studies are a consequence of complex RTK inhibition and not direct PDGFR-β inhibition." (PMID 25361000, 2014). "Studies have demonstrated that FOXC2 can regulate HOTAIR, an oncogenic lncRNA that recruits Polycomb Repressive Complex 2 (PRC2) to silence tumor suppressor genes, facilitating metastasis and EMT activation." (PMID 40781106, 2025). "In the invasive edge, TFs such as FOS, JUN, and FOXC2 are likely driving epithelial-to-mesenchymal transition (EMT), enabling migration, invasion, and metastasis of tumor cells." (PMID 41238550, 2025).